NEAT1 (nuclear paraspeckle assembly transcript 1)
Diseases named in the same sentence as NEAT1 in open-access papers (continued):
Sharing a sentence is not in itself a finding about the gene and the disease.
glioma (continued). "The lncRNA NEAT1 overexpression significantly reversed the decreased FGF-2, TGF-β and VEGF production induced by ISL in the U87 glioma cells, but miR-194-5p mimic attenuated these effects." (PMID 31438982, 2019). "Next, we determined the effects of lncRNA NEAT1 on miR-194-5p expression, and found that ISL upregulated the miR-194-5p expression in the U87 glioma cells." (PMID 31438982, 2019). "Although NEAT1, miR-132 and SOX2 have been proved to play crucial roles in glioma, their regulatory mechanism and interaction still need to be further studied." (PMID 30053878, 2018). "According to another study, nuclear enriched abundant transcript 1 (NEAT1) was upregulated in 15 glioma tissues and 3 glioma cell lines compared to normal brain tissues." (PMID 30217088, 2018). "Studies have identified several common genes and miRNAs that are ceRNA partners of NEAT1 different cancer types, for example, the NEAT1/miR-107/CDK6 (cyclin dependent kinase 6) axis is deregulated in laryngeal squamous cell carcinoma (LSCC) and glioma." (PMID 29702599, 2018). "In four glioma cell lines (U87, U251, SHG44, U-118 MG), the expression of NEAT1 and SOX2 was distinctively elevated compared with normal cell line HA, whereas miR-132 expression in glioma cell lines was significantly lower than that in HA cell line." (PMID 30053878, 2018). "This study was designed to investigate the role of lncRNA NEAT1, miR-132 and SOX2 interaction in glioma." (PMID 30053878, 2018). "Nuclear paraspeckle assembly transcript 1 (NEAT1), a long non-coding RNA, promotes oncogenesis in various tumors, including human gliomas." (PMID 27556696, 2016). "In the current study, we sought to determine the expression and function of NEAT1, let-7e and NRAS in glioma tissues and GSCs." (PMID 27556696, 2016). "In addition, NEAT1 increases β-catenin nuclear transport and H3K27 trimethylation, impacting glioma progression and glycolysis regulation." (PMID 41149459, 2025). "Anyway, the precise function and mechanism of NEAT1 in the development of TMZ resistance in glioma, specifically in GBM, have not been fully elucidated despite the limited number of reports on the process." (PMID 39453684, 2024). "According to the TCGA and CGGA databases, a negative correlation of the NEAT1 expression with the survival outcome of glioma patients was revealed." (PMID 39061140, 2024). "Suppressing NEAT1 impedes the migration and invasion capabilities of glioma cells by modulating the expression of SOX2, targeted by miR-132, underscoring NEAT1’s significance in glioma progression and its potential as a therapeutic target." (PMID 39015773, 2024). "In addition, many lncRNAs, including PTCSC3, NEAT1, and BLACAT1, have been reported to regulate Wnt/β-catenin signaling pathway to affect glioma cell growth, migration, and invasion." (PMID 34923953, 2022). "Studies have shown that NEAT1 is upregulated in glioma tissues compared with adjacent normal tissues." (PMID 36011001, 2022). "The NEAT1/miR-128-3p/ITGA5 axis is essential in the genesis and development of glioma and may be a viable innovative technique for glioma treatment." (PMID 36793341, 2022). "Therefore, a higher level of NEAT1 can promote the proliferation, migration, and epithelial–mesenchymal transition (EMT) process in glioma cells." (PMID 36011001, 2022). "NEAT1 and CDK6 could promote tumorigenesis of glioma cells; additionally, miR‐139‐5p restrained the biological functions of glioma cells." (PMID 34178684, 2021). "NEAT1 may interact with EZH2 and mediate H3K27 trimethylation in their promoters, and NEAT1 was essential for glioma cell proliferation and invasion, since it increased β-catenin nuclear transport while decreasing ICAT, GSK3B, and Axin2 expression." (PMID 37305396, 2021). "Taken together, these data suggest that the overexpression of BZW1 could rescue si-NEAT1-induced glioma cell tumorigenesis inhibition and that NEAT1’s oncogenic activity occurs partly via the miRNA-98-5p/BZW1 axis in glioma cells." (PMID 33393590, 2021).
glioma (continued). "Moreover, NEAT1 can facilitate growth, metastasis, and progression in colorectal cancer (CRC) and glioma cells through activating Wnt/β-catenin signaling." (PMID 34769497, 2021). "As a result, high expression of NEAT1 and lack of miR-128-3p were observed in glioma specimens and cells." (PMID 34263426, 2021). "In GBM, NEAT1 over-expression correlated with clinic-pathological characteristics, such as larger tumor size, higher WHO grade, recurrence, and with a poor prognosis in glioma patients." (PMID 32443824, 2020). "NEAT1, a highly abundant lncRNA in the nucleus, was found to be present at higher levels in glioma than in non-cancerous brain tissues." (PMID 32219093, 2020). "Taken together, these results suggested that HMGB1 could promote the formation of GSCs by primary glioma cells via TLR9 and NEAT1." (PMID 32843056, 2020). "Therefore, ADV infection likely triggers TLR9/MYD88 signaling, which upregulated NEAT1 and activated STAT3, and activated STAT3 further upregulates NEAT1 to form a positive-feedback loop, and promotes GSCs formation from primary glioma cells." (PMID 32843056, 2020). "The interactions between NEAT1, miR-132 and SOX2 in glioma were also novel findings." (PMID 30053878, 2018). "NEAT1 and SOX2 knockdown successfully reduced the invasiveness of glioma cells." (PMID 30053878, 2018). "NEAT1 is upregulated in human GBM tissues and glioma cell lines like U251 and U87." (PMID 30116729, 2018). "Therefore, we investigated the interaction between lncRNA NEAT1, miR-132 and SOX2 in glioma and identified their roles in glioma." (PMID 30053878, 2018). "NEAT1 knockdown could down-regulate SOX2 by up-regulating miR-132, thus suppressing glioma cell growth and invasiveness." (PMID 30053878, 2018). "An increase in NEAT1 expression has also been reported in human glioma tissues compared with non-cancerous brain tissues." (PMID 28293170, 2017). "Furthermore, METTL3 enhances the stability of SOX2 mRNA, protecting glioma stem-like cells from radiation cytotoxicity, and METTL3-induced stabilization of nuclear paraspeckle assembly transcript 1 (NEAT1) and the activation of the miR-3773p/Nampt axis confer neuroprotection in ischemic injury." (PMID 41294873, 2025). "In addition, lncRNA NEAT1 could promote SOX2 expression by inhibiting miR-132, thus promoting glioma development." (PMID 35300348, 2022). "Notably, ITGA5 was depleted by miR-128-3p, whereas NEAT1 would forestall that and sponge miR-128-3p competitively so that ITGA5 could activate FAK signaling pathway and facilitate glioma progression." (PMID 34263426, 2021). "Similarly, NEAT1 knockdown targets miR-132, which regulates the oncogene sex determining region Y-box protein 2 (SOX2) and miR-107, a modulator of cyclin-dependent kinase 6 (CDK6) and CDK14; these findings were closely connected with glioma malignancy." (PMID 33980320, 2021). "Furthermore, NEAT1 distinguishes the survival both in the GBM and lower grade gliomas." (PMID 33317554, 2020). "Therefore, through targeting miR-132, NEAT1 could indirectly regulate SOX2’s expression, thus affecting glioma progression." (PMID 30053878, 2018). "NEAT1 expression was higher in glioma tissues than adjacent noncancerous tissues." (PMID 30116729, 2018). "NEAT1 and SOX2 knockdown could restrain the viability and invasiveness of glioma cells." (PMID 30053878, 2018). "In addition to NEAT1, SOX2 was also over-expressed in glioma as well as other human tumors." (PMID 30053878, 2018). "However, the expression levels of Neat1, Mir142hg, Pvt1, Mir17hg, SNHG12 and Meg3 showed opposite trends, which may correlate with the distinct inflammatory profiles and immunophenotypes of the different glioma models analyzed." (PMID 40527978, 2025).
lung cancer (99 papers, 2016 to 2025). A malignant neoplasm involving the lung. "In examining the genes with the highest fold change in expression between ciliated cells from healthy and IPF tissue, IPF ciliated cells were found to highly express FTO and NEAT1, both markers implicated in lung cancer development." (PMID 35326483, 2022). "At present, there are many studies on the relationship between NEAT1 polymorphism and lung cancer susceptibility, whereas the conclusions are very different." (PMID 33879681, 2021). "The pooled odds ratios with 95% confidence intervals were calculated to estimate the strength of the association between NEAT1 polymorphisms and lung cancer risk." (PMID 33879681, 2021). "Nuclear paraspeckle assembly transcript 1 (NEAT1) polymorphisms were reported to be closely related to lung cancer susceptibility." (PMID 33879681, 2021). "Recently, numerous studies have been performed to detect the association between NEAT1 polymorphisms and lung cancer susceptibility." (PMID 33879681, 2021). "We report here the biological role of nuclear paraspeckle assembly transcript 1 (NEAT1) in the pathogenesis of lung cancer and the underlying mechanisms." (PMID 32296457, 2020). "Functionally, elevated NEAT1 expression is associated with cell proliferation, migration, invasion, cancer stem cell property and chemotherapy resistance in lung cancer." (PMID 33298086, 2020). "Studies have reported that NEAT1 is upregulated in prostate cancer, colorectal cancer and lung cancer, and thus associated with poor prognosis in these cancer patients." (PMID 28615056, 2017). "NEAT1 overexpression is associated with poor prognosis in breast and esophageal cancers, and with progression and metastasis in lung cancer." (PMID 27270317, 2016). "This meta-analysis will summarize the relationship between NEAT1 polymorphism and lung cancer." (PMID 33879681, 2021). "The present study furthered the underlying mechanism of regulatory effect of NEAT1 on lung cancer." (PMID 32296457, 2020). "Apart from this, NEAT1 was also found to contribute to the chemo-/radio-resistance in ovarian cancer, lung cancer and nasopharyngeal carcinoma, which implicated that NEAT1 could be a potential biomarker for chemo-sensitivity." (PMID 27926523, 2017). "NEAT-1 expression is upregulated in many human malignancies, including oesophageal, gastric, and lung cancers." (PMID 39184920, 2024). "This review delves into the pivotal role of the long non-coding RNA NEAT1 in cancer biology, particularly in lung cancer (LC)." (PMID 38343745, 2024). "MALAT1 expression also appears to be tightly linked to increased de-differentiation and increased metastatic phenotypes in lung cancers and, furthermore, NEAT1 is found in CSC fractions of LUAD cells." (PMID 39062685, 2024). "Key lncRNAs such as NEAT1, TUG1, MALAT1, HOTAIR, and GAS5 demonstrate a crucial role in lung cancer progression and serve as powerful prognostic and diagnostic biomarkers." (PMID 39201688, 2024). "NEAT1 was found highly expressed in lung cancer and interacts with DNA methyltransferase DNMT1 to regulate cytotoxic T cell infiltration in lung cancer by inhibiting the cGAS/STING pathway." (PMID 37144123, 2023). "For example, our top-prediction NEAT1 was shown to be important for the viability of lung cancer cells while its knock-down triggered interferon signaling and impaired tumor growth in vivo." (PMID 37420093, 2023). "For example, DNMT1 interacted with NEAT1 to regulate cytotoxic T-cell infiltration in lung cancer via inhibition of the cGAS/STING pathway." (PMID 36226184, 2022). "Suppression of the cGAS-STING pathway by nuclear paraspeckle assembly transcript 1 (NEAT1) results in the promotion of lung cancer growth, in syngeneic models, via inhibition of cytotoxic T cell infiltration." (PMID 35978045, 2022).
lung cancer (continued). "NEAT1 negatively regulated CD8+ T cells in lung cancer cells via increasing CXCL10, CCL5, and IFN-β expression, which directly induced cGAS/STING Signaling, to suppress immune response." (PMID 35047506, 2021). "In lung cancer, lncRNA NEAT1 was proved to be a regulator of ferroptosis sensitivity, and lncRNA MT1DP modulated erastin-induced ferroptosis via miR-365a-3p/NRF2 axis." (PMID 35127813, 2021). "The link between NEAT1 and miR-98 in lung cancer and prostate cancer has been clarified in previous investigations." (PMID 34950596, 2021). "Although they were on the top of the list, long non-coding RNAs (LncRNAs) MALAT1 and NEAT1 have already been characterized as the hallmarks of metastasis in lung cancer and other malignant tumors." (PMID 33144684, 2021). "Knocking down lncRNA NEAT1 constrains the viability, proliferation, and invasion of lung cancer cells, while facilitating the infiltration of cytotoxic T cells in tumor tissue." (PMID 34306024, 2021). "Nuclear-enriched abundant transcript 1 (NEAT1) induces CSC-like traits in lung cancer cells by activating Wnt signaling." (PMID 34949193, 2021). "LncRNA PVT1, SBF2‐AS1, and nuclear paraspeckle assembly transcript 1 (NEAT1) are also involved in this regulatory network of lncRNA‐microRNA‐mRNA and can affect the radiosensitivity of lung cancer cells." (PMID 33931980, 2021). "Accumulating reports indicate that lncRNA NEAT1 works as a sponge for miR-98, downregulating its levels in lung cancer and colon cancer cells." (PMID 34950596, 2021). "Consistently, the expression level of NEAT1 was upregulated in lung cancer cell lines when compared with that in human normal bronchial epithelial cells 16HBE." (PMID 32296457, 2020). "Our results showed that NEAT1 was found to promote cell survival, migration, and invasion in lung cancer cells." (PMID 32296457, 2020). "In lung cancer, nuclear-enriched abundant transcript 1 (NEAT1) has been shown to enhance cisplatin sensitivity via upregulating epigallocatechin-3-gallate (EGCG)-induced CTR1 expression." (PMID 32854207, 2020). "In vitro studies displayed that inhibition of NEAT1 with shRNA resulted in suppression of survival and migration/invasion of lung cancer cells." (PMID 32296457, 2020). "LncRNA NEAT1 contributes to lung cancer cell proliferation and invasion via NEAT1/miR-1224/KLF3 ceRNA pattern." (PMID 32297639, 2020). "For instance, miR-101 and miR-217 regulate the half-life of metastasis associated lung adenocarcinoma transcript 1 (MALAT1) in carcinoma cells, while miR-449a silences the nuclear enriched abundant transcript 1 (NEAT1) in lung cancer." (PMID 31732741, 2020). "The effect of NEAT1 on cell survival and migration/invasion was characterized in lung cancer cell lines with specific shRNA targeting NEAT1." (PMID 32296457, 2020). "Enhanced mRNA and protein levels of CXCL10, CCL5, and IFNβ were observed following silencing of NEAT1 in human and mouse lung cancer cells as measured by qRT-PCR and Western blot analysis, respectively." (PMID 32296457, 2020). "Consistently, we found that NEAT1 was upregulated in lung cancer tissues as well as lung cancer cell lines." (PMID 32296457, 2020). "Our findings demonstrated that NEAT1 interacted with DNMT1 to regulate cytotoxic T cell infiltration in lung cancer via inhibition of cGAS/STING pathway." (PMID 32296457, 2020). "RNA immunoprecipitation assay confirmed that NEAT1 was able to bind to DNMT1 in both lung cancer cells." (PMID 32296457, 2020). "For example, the lncRNAs MALAT1 and NEAT1 play important roles in lung cancer cell proliferation, cell cycle progression, and apoptosis, as well as tumor progression and prognosis." (PMID 32819367, 2020).
lung cancer (continued). "NEAT1 inhibits the cytotoxic T cell infiltration in the lung cancer microenvironment to promote tumor growth in the syngeneic mouse models." (PMID 33643304, 2020). "NEAT1 is aberrantly expressed in many malignant human diseases (including lung cancer) and functions as an oncogene." (PMID 32819367, 2020). "Another study has indicated that the cGAS-STING signaling pathway inhibition due to upregulated nuclear paraspeckle assembly transcript 1 (NEAT1) in the lung cancer cells and tissues." (PMID 33643304, 2020). "The data showed that the downregulation of NEAT1 showed antitumor effect in M109 syngeneic models, suggesting that NEAT1 was able to promote lung cancer growth." (PMID 32296457, 2020). "In the present study, the biological function and mechanism of NEAT1 in lung cancer were investigated." (PMID 32296457, 2020). "Taken together, these data suggest NEAT1 knockdown drives an adaptive T cell tumor-specific immune response that results in tumor inhibition of lung cancer." (PMID 32296457, 2020). "Although it was reported that NEAT1 promotes the apoptosis, proliferation, and metastasis of lung cancer cells, the involvement of NEAT1 in immune oncology remains to be explored." (PMID 32296457, 2020). "Both miR-101 and miR-217 negatively regulate metastasis associated with lung adenocarcinoma transcript 1 (MALAT1) in carcinoma cells, and miR-449a inhibits the expression of nuclear enriched abundant transcript 1 (NEAT1) lncRNA in lung cancer." (PMID 30781588, 2019). "Among these miRNAs, NEAT1 is found to act as a competing endogenous lncRNA for miR-98-5p in lung cancer." (PMID 31481527, 2019). "Previous studies have demonstrated that NEAT1 was continuously expressed in many cancer cell lines, such as lung cancer and gastric cancer." (PMID 31462890, 2019). "LncRNA NEAT1 expression was significantly upregulated in lung cancer cells, and NEAT1 significantly accelerated tumor growth in vivo." (PMID 30925672, 2019). "Previous studies showed that lncRNA NEAT1 played vital roles in the development of tumors, such as lung cancer, hepatocellular carcinoma, colorectal cancer and squamous cell carcinoma." (PMID 31481527, 2019). "More importantly, NEAT1 expression is also up-regulated in lung cancer tissues or plasma; increased NEAT1 expression is related to unfavorable prognosis in patients with lung cancer, thus is regarded as a diagnosis marker." (PMID 29788922, 2018). "LncRNA nuclear enriched abundant transcript 1 (NEAT1) is highly expressed in lung cancer and promotes lung cancer cell proliferation and migration." (PMID 29788922, 2018). "In lung cancer, NEAT1 acts as an oncogenic lncRNA through affecting cancer cell proliferation, invasion and migration via different downstream signaling pathways." (PMID 29788922, 2018). "Recent reports have suggested that NEAT1 contributes to tumorigenesis in various cancers, such as lung cancer, prostate cancer, hepatocellular cancer, laryngeal squamous cell cancer, and gastric cancer." (PMID 29515109, 2018). "The data suggest that LPS promotes p65 nucleus translocation, followed by activation of NEAT1 expression in lung cancer cells." (PMID 29788922, 2018). "We first examined NEAT1 expression in lung adenocarcinoma tissues and its correlation with clinic features in patient with lung adenocarcinoma; next, the detailed function of NEAT1 in lung cancer cell proliferation and migration was assessed." (PMID 29788922, 2018). "NEAT1 is highly expressed in lung adenocarcinoma tissues and promotes lung cancer cell proliferation and migration." (PMID 29788922, 2018).